NLRP3 (NLR family pyrin domain containing 3)
Diseases named in the same sentence as NLRP3 in open-access papers (continued):
Sharing a sentence is not in itself a finding about the gene and the disease.
myocardial ischemia (continued). "One of the recently identified proinflammatory signaling pathways involved in myocardial ischemia reperfusion injury is NLRP3 inflammasome, that inhibition of NLRP3 activation limited inflammatory injury following myocardial ischemia reperfusion." (PMID 27929137, 2016). "Additionally, recent findings demonstrated that carvacrol attenuated isoproterenol-induced myocardial ischemia via activation of PPARγ and Nrf2, along with downregulation of NLRP3." (PMID 40430456, 2025). "Moreover, deubiquitinating enzyme USP25 improves myocardial ischemia-reperfusion injury by deubiquitinating NLRP3 and negatively regulating the activity of the NLRP3 inflammasome in cardiomyocytes." (PMID 40413536, 2025). "Moreover, the lactate dehydrogenase encoding gene LDHA, which catalyzes the conversion between pyruvate and lactic acid, can induce myocardial pyroptosis by enhancing NLRP3 lactation, thereby promoting myocardial ischemia–reperfusion injury." (PMID 40873619, 2025). "Our findings elucidated that tilianin disrupted the NLRP3-NEK7 interaction, proposing a supplemental mechanism by which tilianin treatment could mitigate NLRP3 inflammasome activation and alleviate myocardial ischemia/reperfusion injury." (PMID 39508038, 2024). "First, Sal B can further induce NLRP3 inactivation by inhibiting intracellular ROS production during myocardial ischemia, increasing the mitochondrial membrane potential, regulating the expression levels of SIRT1, Parkin, and PINK1 proteins, and promoting mitochondrial autophagy." (PMID 39323645, 2024). "Moreover, cardiac fibroblasts NLRP3 inflammasomes activation exacerbated myocardial ischemia–reperfusion injury." (PMID 39604027, 2024). "Researchers have demonstrated that it can improve myocardial ischemia–reperfusion injury in rats and enhance heart function by inhibiting the activation of NLRP3 inflammasomes. β-Sitosterol is one of the phytosterol constituents belonging to the tetracyclic triterpenoids." (PMID 39432628, 2024). "As one of highly enriched miRNAs in hUC-MSC-sEVs, miR-100-5p delivered by MSC-sEVs was found to protect cartilage from damage in osteoarthritis, and inhibit NLRP3 inflammasome activation and suppress cytokine release to ameliorate myocardial ischemia/reperfusion injury." (PMID 35874782, 2022). "FTZ treatment could inhibit cardiac ischemia-induced pyroptosis by downregulating NLRP3 and related cytokines including 1L-1β and 1L-18, which mitigate cardiac dysfunction." (PMID 36387353, 2022). "In addition, NLRP3, caspase-1 cleavage, and particularly IL-1β were induced early during myocardial ischemia/infarction." (PMID 34752417, 2022). "We propose a hypothesis that cardiomyocytes produce pyrolysis after myocardial ischemia reperfusion, and Sevoflurane reduces cellular inflammation and pyrolysis by inhibiting NLRP3 expression, which explains the anti-MIRI effect of Sevoflurane." (PMID 34765646, 2021). "However, myocardial NLRP3 and IL‐1β were shown to be upregulated in response to myocardial ischemia." (PMID 34472725, 2021). "However, outcomes from experiments manipulating the NLRP3 inflammasome in myocardial ischemia remain indefinite." (PMID 32545788, 2020). "This review discusses the mechanisms of NLRP3 inflammasome activation and the relationship between the inflammasome and CVDs, including coronary atherosclerosis, myocardial ischemia/reperfusion, cardiomyopathies, and arrhythmia, as well as CVD-related treatments." (PMID 31354731, 2019). "We hypothesize that the mechanism of salvianolic acid B against myocardial ischemia may be related to the inflammatory cascade induced by TLR4/NF-κB/NLRP3 signaling pathway." (PMID 31816891, 2019). "Therefore, modification of cysteines on Keap1 to affect the Nrf2-related antioxidative signaling pathway might ameliorate NLRP3 inflammasome-related myocardial ischemia reperfusion." (PMID 33391509, 2021).
myocardial ischemia (continued). "However, whether Sal B could reduce myocardial ischemia injury by inhibiting the activation of NLRP3 inflammasome remains unknown." (PMID 31816891, 2019). "Myocardial ischemia triggered the activation of the TLR4/MyD88/NF-κB signaling pathway, which facilitated the assembly and activation of the NLRP3 inflammasome, thereby exacerbating cardiac inflammation." (PMID 39925805, 2025). "NLRP3 in myocardial ischemia–reperfusion injury (MIRI) will become a hot research topic, and translational research on NLRP3 inhibitors in MIRI will benefit a greater number of patients." (PMID 40018377, 2025). "Exhibits cardioprotective characteristics by suppressing NLRP3 inflammasome activation and GSDMD-mediated pyroptosis in cardiomyocytes, presenting potential uses for myocardial ischemia/reperfusion damage." (PMID 40191425, 2025). "In Myocardial ischemia/reperfusion injury, Hydroxysafflor yellow A can activate AMPK to reduce the NLRP3 inflammasome via blocking the mTOR pathway." (PMID 35873572, 2022). "Inhibition of NLRP3 using MCC950 demonstrates beneficial effects in fulminant hepatitis and in myocardial ischemia reperfusion." (PMID 33716981, 2021). "Inflammation in general and the NLRP3 inflammasome in particular are involved in the pathophysiology of cardiovascular diseases, including HF18 and myocardial ischemia." (PMID 34472725, 2021). "A plethora of inhibitors proposed to hamper post-myocardial ischemia damage inhibit hypoxia-induced TXNIP and NLRP3 expressions." (PMID 33567593, 2021). "Preventing the interaction between TXNIP and NLRP3 suppresses the ROS-TXNIP-NLRP3 pathway and alleviates myocardial ischemia/reperfusion injury." (PMID 33567593, 2021). "In a rat model of myocardial ischemia/reperfusion injury, it was found that exosomes derived from M2 macrophages deliver microRNA-148a and alleviate myocardial ischemia/reperfusion injury by inhibiting thioredoxin interacting protein (TXNIP) and the TLR4/NF-jB/NLRP3 inflammasome signalling pathway." (PMID 38622659, 2024). "FTO inhibits NLRP3-mediated pyroptosis through the suppression of β-catenin ubiquitination and degradation by decreasing the stability of CBL mRNA, contributing to the alleviation of cardiac ischemia/reperfusion injury." (PMID 38663914, 2024). "Consistently, time of cardiac ischemia/reperfusion and subsequent SR9009 treatment affect heart function recovery, the best response being obtained when Rev-erb expression is at its highest, ie when NLRP3 expression is at its lowest." (PMID 33716981, 2021).
ulcerative colitis (105 papers, 2015 to 2026). An inflammatory bowel disease involving the mucosal surface of the large intestine and rectum. "Bioinformatics analysis revealed high expression levels of several inflammation-associated genes, including TNF-α, HMGB1, and NLRP3, in the colonic tissues of patients with ulcerative colitis." (PMID 40688353, 2025). "CASP1, encoding caspase 1, is a key component of NLRP3 inflammasomes and is positively related to active ulcerative colitis." (PMID 36619896, 2022). "Two more recent studies showed elevated serum NLRP3 levels associated with severity of diseases such as ulcerative colitis and polyradiculoneuropathy." (PMID 34362072, 2021). "Several inflammatory conditions are associated with NLRP3 inflammasome assembly and activation, including gout, hepatitis, and ulcerative colitis." (PMID 34489707, 2021). "In the gut, NLRP3 is key in maintaining intestinal homeostasis; NLRP3-deficient mice were more susceptible to ulcerative colitis and displayed reduced IL-1β, IL-10, and TGF-β." (PMID 32098318, 2020). "Furthermore, genetic variations of IL-18 and NLRP3 have been associated with the development of human Crohn’s disease, whereas an involvement of the NLRP3 inflammasome in the development of ulcerative colitis (UC) is still a matter of debate." (PMID 25799280, 2015). "NLRP3 inflammasomes respond to a variety of endogenous (damage-associated molecular patterns) and exogenous (pathogen-associated molecular patterns) stimuli, and play crucial roles in host defense against pathogens and multiple diseases such as ulcerative colitis (UC)." (PMID 28380426, 2017). "The activation of NLRP3 inflammasome contributes to the development of numerous chronic inflammatory diseases, including ulcerative colitis and stress-induced anxiety." (PMID 41514502, 2026). "We found significant differences in NLRP3 levels between gastric controls, colon tumors, ulcerative colitis patients, and healthy colons." (PMID 41003004, 2025). "Our study is limited due to a small sample size, while still providing preliminary results and an initial framework for understanding the interplay between α7nAChR and NLRP3 in gastrointestinal cancers and ulcerative colitis." (PMID 41003004, 2025). "Although the sample size of this study was small, it provides clinical evidence supporting the role of NLRP3 and HMGB1 in ulcerative colitis and suggests their potential as novel diagnostic markers for the disease." (PMID 40688353, 2025). "In ulcerative colitis models induced by dextran sulfate sodium, SAL’s defensive effects were partly linked to its capability to hinder the NLRP3 inflammasome." (PMID 40417000, 2025). "Its association with IBD has been suggested, with studies reporting upregulation of NLRP3 and IL-1β in adult patients with ulcerative colitis (UC) and Crohn’s disease." (PMID 41149694, 2025). "Previous studies have demonstrated that activation of NLRP3 inflammasome plays a critical role in the pathogenesis of ulcerative colitis (UC)." (PMID 40919130, 2025). "Articles from PubMed and Web of Science on NLRP3 inflammasome, ulcerative colitis, Crohn’s disease, pancreatitis, and NAFLD were summarized to analyze the data and conclusions carefully to ensure the comprehensiveness, completeness, and accuracy of the review." (PMID 40860651, 2025). "For example, the potential target of Shaoyao decoction for the treatment of ulcerative colitis was screened by network pharmacology to be NLRP3, and the potential therapeutic pathway was MKP1/NF-κB." (PMID 40242756, 2025). "We next examined NR4A1 and NLRP3 activation in intestinal tissue sections from patients with ulcerative colitis and found increased activation of these proteins in CD68+ macrophages in active UC compared to remission." (PMID 40596758, 2025). "In ulcerative colitis mice model, the abundance of Alistipes is increased and the expressions of NLRP3 and caspase-1 are elevated." (PMID 40104594, 2025).
ulcerative colitis (continued). "Although an increase in inflammasomes was detected between cancerous and healthy tissue, an increase in NLRP3 levels was found in ulcerative colitis patients." (PMID 41003004, 2025). "Our results confirm that Krüppel‐like factor 4 can positively regulate the expression of TXNIP and regulate the pyroptosis process of ulcerative colitis through the TXNIP/NLRP3 pathway." (PMID 38411328, 2024). "The NLRP3 inflammasome drives release of pro‐inflammatory cytokines including interleukin (IL)‐1β and IL‐18 and is a potential target for ulcerative colitis (UC)." (PMID 37962000, 2023). "Among NLRPs, the expression of NLRP3 has been demonstrated to be upregulated in ulcerative colitis, leading to tissue injury and clinical characterizations." (PMID 37833958, 2023). "Overproduction of IL-1β dependent on the NLRP3 inflammasome is characteristic of Crohn’s disease, and disruption of the NLRP3 inflammasome also alleviates ulcerative colitis." (PMID 36845112, 2023). "The overactivation of NLRP3 inflammasome in intestinal epithelial cells (IECs) is among the important reasons for severe inflammation in ulcerative colitis (UC)." (PMID 35860016, 2022). "Studies have also shown that calcitriol is capable of inhibiting NLRP3 inflammasome activation and its downstream cytokine signaling in mouse models of liver injury and fibrosis, ulcerative colitis, and diabetic retinopathy." (PMID 35712242, 2022). "Mechanism of electroacupuncture targeting NLRP3 inflammasome in the treatment of ulcerative colitis and non-alcoholic fatty liver disease." (PMID 36337711, 2022). "Due to the decreased activity of AMPK in the current model of ulcerative colitis, the mTOR activity was enhanced, which also led to an activation in NLRP3 inflammasome expression." (PMID 34489707, 2021). "Moxibustion encourages the recovery of colon injury probably by regulating the expression of NLRP3 protein in ulcerative colitis rats through miR7/RNF183/NF-κB signaling pathway." (PMID 34777536, 2021). "The efficacy of NLRP3 inhibitors has been examinutesed in experimental models of ulcerative colitis." (PMID 30823406, 2019). "Our in vitro results with glyburide shows that it is effective in inhibiting NLRP3 inflammasome in a spontaneous ulcerative colitis mouse model." (PMID 29872077, 2018). "Experiments have demonstrated that the anti-inflammatory effects achieved by inhibiting HMGB1 binding to TLR4 and suppressing the activation of the NF-κB/NLRP3 inflammasome pathway can ameliorate colonic mucosal barrier disruption and neutrophil recruitment in ulcerative colitis." (PMID 40688353, 2025). "Additionally, it emphasizes the roles and mechanisms of the NLRP3 inflammasome in common inflammation-related gastrointestinal diseases such as ulcerative colitis, Crohn’s disease, pancreatitis, and non-alcoholic fatty liver disease (NAFLD)." (PMID 40860651, 2025). "In summary, this study comprehensively reviews the biological characteristics of the NLRP3 inflammasome, with a focus on its roles and mechanisms in several inflammation-related gastrointestinal diseases, including ulcerative colitis, Crohn’s disease, pancreatitis, and NAFLD." (PMID 40860651, 2025). "In conditions such as Crohn’s disease, ulcerative colitis, renal disease, as well as infections with pathogens NLRP3 and its downstream cytokine IL-1β are essential for preserving intestinal epithelial structure, promoting barrier repair, and ensuring tissue homeostasis." (PMID 41394833, 2025). "The capacity of SA to inhibit the activation of the NLRP3 inflammasome was previously reported in rats with diabetic atherosclerosis and in a Kunming mouse model of dextran sodium sulfate-induced ulcerative colitis as well as an intestinal fibrosis model in C57/6BL mice." (PMID 38662166, 2024). "This study aimed to investigate whether OMT could attenuate ulcerative colitis by inhibiting the NOD-like receptor family pyrin domain containing three (NLRP3) inflammasome-mediated pyroptosis." (PMID 38930963, 2024).
ulcerative colitis (continued). "In summary, these results indicated that OMT could attenuate ulcerative colitis through inhibiting pyroptosis mediated by the NLRP3 inflammasome." (PMID 38930963, 2024). "The NLRP3 inflammasome complex plays an important role in innate immunity; however, its misregulation can be responsible for the apparition of various pathologies such as ulcerative colitis." (PMID 36834883, 2023). "As NLRC4 and NLRP3 have been demonstrated to be able to recruit the same inflammasome complex, the signaling of NLRC4 in ulcerative colitis may be similar to that of NLRP3." (PMID 37833958, 2023). "The GG and CG genotypes of NLRP3 rs10754558 were strongly related to ulcerative colitis." (PMID 36836487, 2023). "However, NLRP3 was also found to act as a negative regulator in the initial immune response in ulcerative colitis." (PMID 37833958, 2023). "Additionally, NLRP3 inflammasome has been investigated relatively to having a role in the pathogenesis of ulcerative colitis, as it is responsible for activating the expression of caspase-1, producing IL-1β and IL-18 and starting the inflammatory process." (PMID 35745756, 2022). "NLRP3 inflammasome is responsible for increased production of IL-1β, and suppressing NLRP3 inflammasome activation by inhibiting MKP1/NF-κB pathway could attenuate DSS-induced ulcerative colitis." (PMID 36339623, 2022). "The research aimed to investigate the influence of moxibustion on the activation of NLRP3 inflammasome and its mechanism in treating ulcerative colitis by observing miR7/RNF183 inducing IκB α ubiquitination to regulate NF-κB signaling pathway in an ulcerative colitis rat model." (PMID 34777536, 2021). "NLRP3 mediates Dextran Sodium Sulfate (DSS)-induced ulcerative colitis in mice." (PMID 33918290, 2021). "We speculate that DHT may ameliorate DSS-induced experimental ulcerative colitis by inhibiting the NLRP3 inflammasome." (PMID 34721038, 2021). "It has been confirmed that DSS-induced ulcerative colitis is an NLRP3-dependent disease." (PMID 34721038, 2021). "We investigated roles of the NLRP3 inflammasome in the pathogenesis of ulcerative colitis (UC)." (PMID 27966619, 2016). "Finally, as dietary anthocyanins prevent many inflammatory diseases in vivo, such as ulcerative colitis and cerebral ischemia-reperfusion injury, it should be determined whether PS is effective in vivo against NLRP3 inflammasome-mediated inflammation." (PMID 33613822, 2021). "Therefore, suppressing the NLRP3 pathway and the subsequent cytokine expression might be beneficial for improving the symptoms of ulcerative colitis and preventing its recurrence." (PMID 33859564, 2021). "AR alleviates ulcerative colitis by targeting PKM2 to inhibit the NF-κB and NLRP3 pathways, thereby reducing inflammation and modulating immune responses." (PMID 41158126, 2025). "A prospective observational study revealed elevated serum levels of NLRP3 and HMGB1 in patients with ulcerative colitis, which were positively correlated with disease severity." (PMID 40688353, 2025). "In ulcerative colitis, RING finger protein 31, an E3 Ub ligase, interacts with NLRP3 through the RING-between-RING finger domain, resulting in K63-linked ubiquitination of NLRP3 and its subsequent stabilization." (PMID 40307577, 2025). "Ulcerative colitis (UC) is characterized by complex immunological interactions involving CD4 T cell subsets and the NLRP3 inflammasome, which influence inflammatory responses." (PMID 39833691, 2025). "The underlying molecular mechanisms of GB1 appear to involve the suppression of NLRP3 inflammasome activation, reduction in pro-inflammatory mediators, and the mitigation of DSS-induced ulcerative colitis." (PMID 40362256, 2025). "A study showed that Genistein can inhibit NLRP3 activation and protect DSS-treated mice from ulcerative colitis." (PMID 33918290, 2021).
ulcerative colitis (continued). "In dextran sulfate sodium-induced ulcerative colitis models, the protective effects of SAL were in part dependent on its inhibitory effects on the NLRP3 inflammasome." (PMID 34457117, 2021). "For studying how NEK7 affected the pyroptosis in IBD, we first examined the mRNA expression and protein levels of NEK7, as well as key factors in pyroptosis, including Caspase-1, NLRP3, and GSDMD, in control and ulcerative colitis tissues in IBD patients." (PMID 31787755, 2019). "The mRNA expression of NEK7, Caspase-1, NLRP3, and GSDMD showed to be remarkably increased in ulcerative colitis tissue samples than that in control tissues." (PMID 31787755, 2019). "Inflammatory colon tissue from patients who suffered from ulcerative colitis is filled with large numbers of GPR84-positive macrophages, whose involvement in the inflammatory response may depend on the activation of NLRP3 inflammasome." (PMID 36177003, 2022). "Our data shows that the NLRP3 inflammasome plays a negative role in the chronic phase of ulcerative colitis in Winnie." (PMID 29872077, 2018). "Moreover, the ability of MCC950 to suppress both translational and transcriptional IL-1β and IL-18 of canonical and noncanonical NLRP3 inflammasome in the colon may be promising in inflammatory intestinal diseases other than ulcerative colitis." (PMID 29872077, 2018).